MMP9 (matrix metallopeptidase 9)
Diseases named in the same sentence as MMP9 in open-access papers (continued):
Sharing a sentence is not in itself a finding about the gene and the disease.
COVID-19 (continued). "Overall, in both COVID-19 and normal conditions, the number of interacting residues and surface area was higher for MMP9 compared to MMP7 group." (PMID 38803919, 2024). "At first, we demonstrated that MMP-2, MMP-9, and TIMP-1 were elevated among COVID-19 patients and associated with COVID-19 severity, which is consistent with altered extracellular matrix remodelling." (PMID 37509076, 2023). "In the acute stage of COVID-19, CSF levels of MMP-9 were found to increase and related to different inflammatory cytokines as well as to COVID-19 severity." (PMID 37759493, 2023). "Our data underline the detrimental effects of MMP-9, including BBB disruption and inflammation, in the acute phase of COVID-19 associated with astrocyte damage." (PMID 37759493, 2023). "By contrast, a previous study has indicated a decrease in plasma MMP-2 and an increase in plasma MMP-9 in COVID-19." (PMID 36835000, 2023). "Our current study, for the first time, provides evidence on MMP9′s involvement in regulation of mitochondria-related functions and COVID-19 disease progression." (PMID 36768847, 2023). "Matrix metallopeptidase 9 (MMP9) was found in five of the top 10 upregulated pathways, indicating its potential as therapeutic target against COVID-19." (PMID 36768847, 2023). "Thus, despite the small sample size, we observed a positive correlation between the CSF levels of sCD163 and MMP-9, underlining that increased CSF levels of sCD163 and MMP-9 might also contribute to the infiltration of monocytes to the CSF in COVID-19 patients." (PMID 37759493, 2023). "Upregulated MMP-9 genes in COVID-19 patients, together with an increased level of MMP-9, was associated with a risk of respiratory failure." (PMID 36831321, 2023). "Herein, we investigated the plasma levels of MMP-9, TIMP-1 as well as the plasma activity of MMP-2 and MMP-9 in a cohort of well-characterized patients with COVID-19 at an acute stage of the disease and after three months from hospital discharge." (PMID 37509076, 2023). "Recent studies proposed that COVID-19 facilitates BBB disruption by increasing the expression of matrix metalloproteinase-9 (MMP-9) which leads to basement membrane degradation." (PMID 37828990, 2023). "In lung tissue from COVID-19 patients, the MMP-9 gene was up-regulated, and protein contributed to cytokine recruitment." (PMID 37509076, 2023). "In alveoli infected by COVID-19, there is an increase in inflammatory cells that release MMP-9, resulting in alveolar capillary destruction and consequent lung injury." (PMID 37372128, 2023). "A marked increase in plasma levels of MMP-9, a gelatinase, was observed in patients with COVID-19 compared to healthy controls." (PMID 37372128, 2023). "We observed increased levels of plasma MMP-2 and comparable levels of plasma MMP-9 in COVID-19 with pneumonia compared to healthy controls." (PMID 36835000, 2023). "Both PPIA and MMP-9 in hospitalized COVID-19 patients are substantially higher than ALS patients, characterized by severe neurodegeneration, and healthy controls." (PMID 36591311, 2022). "BAL fluid levels of TIMP-1/MMP-9 complexes were significantly elevated in COVID-19 patients having a bacterial-fungal coinfection compared with COVID-19 patients having a bacterial coinfection." (PMID 34793331, 2022). "Another study described the immune-based signature of COVID-19 patients, relating serum MMP9 levels with the severity of COVID-1911." (PMID 35075175, 2022). "High serum levels of MMP7 and MMP9 and the levels of macrophages activation factors, and severity of COVID-19 in obese-diabetic patients were associated with ARDS in COVID-19 patients with risk factors." (PMID 35893698, 2022). "Metalloproteases have a longstanding link to the progression of respiratory damage, and MMP-2, MMP-3, MMP-7, and MMP-9 have all been shown to correlate with COVID-19 severity." (PMID 36298651, 2022).
COVID-19 (continued). "Plasmatic matrix metalloproteinase-9 (MMP-9) was likewise increased in COVID-19 patients which induced platelet and neutrophil activation, and NETs formation in vitro." (PMID 35720378, 2022). "Presented data describe for the first time the high-level systemic MMP-9/BDNF ratio in patients with COVID-19." (PMID 36438922, 2022). "MMP-9 activates signalling molecules such as cytokines or chemokines thus contributing to the development of “cytokine storm” in COVID-19." (PMID 36438922, 2022). "It has been observed that in lung tissue from COVID-19 patients the MMP9 gene is up-regulated, and the protein contributes to the cytokine recruitment." (PMID 35075175, 2022). "To better define the role of MMP3 and MMP9 as biomarkers of COVID-19 outcome, we studied serum levels of these proteins in 108 patients with COVID-19 and in 48 healthy subjects." (PMID 35075175, 2022). "Severe COVID-19 shared many characteristics with sepsis and plasma MMP-9 and tissue inhibitor of matrix metalloproteinase-1 (TIMP-1) have been also proposed as septic biomarkers." (PMID 36523781, 2022). "A distinct increase in circulating MMP9 has been identified in COVID-19 patients with respiratory failure." (PMID 39086962, 2022). "In patients with severe COVID-19, both MMP-2 and MMP-9 levels in circulation were altered and associated with the risk of in-hospital death." (PMID 36482481, 2022). "We studied serum MMP3 and MMP9 as potential biomarkers of COVID-19 severity, in 108 hospitalized patients with different World Health Organization (WHO) severity stage and in 48 controls." (PMID 35075175, 2022). "Significantly increased levels of the metalloproteinase inhibitor tissue inhibitor of metalloproteinases 1 (TIMP-1) and of TIMP-1 in complex with MMP-9 were found in COVID-19 BAL fluids compared with influenza BAL fluids." (PMID 34793331, 2022). "The primary aim of this study was to explore CSF and plasma NfL levels as well as CSF MMP-2 and MMP-9 levels in COVID-19 patients with severe neurological symptoms." (PMID 36010557, 2022). "This disease mechanism is complementary to the COVID-19 model resulting in barrier dysfunction through downregulation of TJ proteins and induction of MMP9." (PMID 39086962, 2022). "A multivariable analysis of patients’ first samples associated an increase of CCL2, IL-15, secreted tumor necrosis factor receptor superfamily member 1A sTNFRSF1A, IL-6, MMP-9, IL-2, or IL-10 with COVID-19 mortality." (PMID 33800947, 2021). "Relative to HCs, significantly elevated concentrations of MMP-9:NGAL heterodimers and an increased MMP-9:TIMP-1 ratio have been detected in COVID-19 patients." (PMID 34149717, 2021). "There is a distinct and early increase in circulating MMP-9 in COVID-19 patients with respiratory failure." (PMID 33800947, 2021). "An increase in matrix metalloproteinase 9 (MMP-9) was reported in COVID-19 patients with respiratory failure and during RSV infection." (PMID 35164569, 2021). "When evaluating the immunoexpression of α-SMA, CD44v6, and MMP-9, it was noted that they were elevated in the COVID-19 group." (PMID 35008594, 2021). "A study of 185 molecules was carried out for the treatment of COVID-19 in a somewhat more sophisticated contribution, among which stood out, for their better complementarity with matrix metallopeptidase 9 (MMP9), chloroquine and melatonin." (PMID 35723382, 2021). "Indeed, the increase of MMP-9 expression and activity correspond to an increase of the inflammatory state in pathology, so much so that it has even been recently proposed, together with other NF-kB-dependent biomarkers, as a signature associated with mortality in COVID-19 patients." (PMID 35723387, 2021). "The analysis of its function shows that the signal receptor binding function mediated by CCL2 and MMP9 is the potential mechanism of the host factor interaction network between COVID-19 and COPD." (PMID 35002688, 2021).
COVID-19 (continued). "For example, F-Gal-9 can be cleaved by MMP9, which is highly increased in the plasma of COVID-19 patients, resulting in the abundance of T-Gal-9 in COVID-19 patients." (PMID 33947753, 2021). "DrugBank lists inhibitors of MMP9 such as marimastat and minocycline, which can be considered for treatment of COVID-19." (PMID 32595353, 2020). "This prospective longitudinal study investigates the sustained dysregulation of matrix metalloproteinases (MMP)-2 and MMP-9 and its relationship with evolving systemic inflammation and endothelial dysfunction in convalescent COVID-19 patients, with comparative analysis to IPF." (PMID 41598609, 2026). "Moreover, LPS-induced surface expression of TLR-4 and COVID-19 S1 protein-induced MMP-9-related gelatinolysis were abrogated by benzydamine under the high-glucose condition." (PMID 41756532, 2026). "Perhaps, the changes in MMP9 may not only explain the involvement in post-COVID-19 GBS but may allow for the identification and novel alternate therapeutic approach against this disease." (PMID 40433617, 2025). "Similarly, it has been reported that serum MMP-3 levels increased progressively with the severity of COVID-19, while MMP-9 levels were significantly higher in patients with severe forms of the disease, although they did not correlate directly with severity." (PMID 40943488, 2025). "Research on the interaction between MMP7/MMP9 and FasL in COVID-19 is still relatively limited." (PMID 38803919, 2024). "Moreover, in both COVID-19 and normal conditions, the number of interacting residues and surface area was higher for MMP9 compared to MMP7 group." (PMID 38803919, 2024). "As we elaborated on RAS signaling we observed that stress and inflammation caused by COVID-19 can even induce a state of amplified cellular survival, proliferation and migration signaling, as evidenced also by the elevated EGFR, MMP9, and other survival factors." (PMID 39502570, 2024). "Research has previously demonstrated the neuroimmune involvement of MMP9 in COVID-19." (PMID 38803919, 2024). "The COVID-19 MMP9-FasL group had more H-bonds compared to MMP7-FasL group (12 vs. 7)." (PMID 38803919, 2024). "Our study provided insights into the interaction between MMP7/MMP9 and FasL in COVID-19." (PMID 38803919, 2024). "Elevated levels of MMP7 and MMP9 have been observed in severe cases of COVID-19." (PMID 38803919, 2024). "While there is currently limited information on the specific interaction between MMP7/MMP9 and FasL in COVID-19, it is possible that they may act synergistically or independently in the immune response and tissue damage observed in severe cases of the disease." (PMID 38803919, 2024). "However, the human MMP family consists of several genes, and herein we show increased transcript levels of MMP-19, MMP-23B and MMP-25 in relation to disease severity in PBMC from COVID-19 patients, underscoring a role for MMPs beyond that of MMP-9 in COVID-19." (PMID 38957465, 2024). "We also predicted that the ratios of BDNF and NFL with MMP-2 and MMP-9 could be considered early predictors of COVID-19 mortality." (PMID 36831321, 2023). "Considering all COVID-19 patients in terms of hospital admissions, positive correlations between the plasma levels of MMP-9 and WBC absolute count (ρ = 0.4794, p < 0.0001), N absolute count (ρ = 0.5403, p < 0.0001), NLR (ρ = 0.4261, p < 0.0001) and CRP (ρ = 0.2335, p = 0.0132) were found." (PMID 37509076, 2023). "Furthermore, a study conducted by Springall and collaborators revealed an intriguing association of IL-6, MMP9, and other cytokines with CD147, a molecule proposed as a potential entry point for the host receptor in COVID-19." (PMID 37764186, 2023). "Chronic activation of MMP-9 can result in the release of pro-fibrotic markers leading to increasing fibroblasts released, promoting fibrogenesis and pulmonary stiffening in diabetic patients, making them more vulnerable to infections, for example COVID-19." (PMID 37372128, 2023).
COVID-19 (continued). "sIL-2R processed by MMP-9 in inflamed lung tissues and/or on infiltrated lymphocytes, as observed in other diseases, might be released in COVID-19 with pneumonia in our study." (PMID 36835000, 2023). "Our current study further supports the pivotal role of MMP9 in modulating immunometabolism via endocrine signaling pathways and could be a potential therapeutic target against severe COVID-19." (PMID 36768847, 2023). "A literature search revealed only a single study, by Ueland et al9., on MMP-9 in COVID-19." (PMID 37545954, 2023). "Another limitation of the current study is that we are not able to discern if upregulated expression of MMP9 and its associated signaling pathways in the severe COVID-19, is because of increased neutrophil population or cell-specific increased expression." (PMID 36768847, 2023). "The downregulation found in the three studies reviewed, one in severe COVID-19, could indicate an increase of MMP-9 in these patients prompting long term consequences in the PNS, leading to the appearance of peripheral pain." (PMID 36834984, 2023). "Another study has also reported higher levels of serum MMP-9 in severe COVID-19." (PMID 36835000, 2023). "Other data showed that the matrix metalloproteinase-9 (MMP-9)/BDNF ratio predicts more severe COVID-19 outcomes as MMPs may contribute to the tissue damage induced by COVID-19 as well as to the alteration of blood–brain barrier integrity." (PMID 36831321, 2023). "Furthermore, MMP-9 levels increased while MMP-2 levels decreased in COVID-19 patients, which is consistent with HCoV-OC43 infection in MRC-5 cells." (PMID 37447286, 2023). "Finally, the records in the literature corroborate that MMP-9 expression remained altered in the post-mortem of COVID-19." (PMID 37372128, 2023). "Our study is the first to investigate the relationship between COVID-19 and MMP-9 and TIMP-1." (PMID 37545954, 2023). "Circulating MMP-9 was further measured in COVID-19 patients in addition to the MMP-3 to see if they could predict the severity of the disease as assessed by the World Health Organization (WHO) severity stage." (PMID 36482481, 2022). "Degradation of extracellular collagen, elastin and connexins by MMP-9 are emphasized with rapid turnover of stiffer collagen, that could be an inducer of fibrosis and numerous complications in COVID-19." (PMID 36438922, 2022). "The increase of serum/plasma levels of MMP3 and MMP9 during COVID-19 was already reported." (PMID 35075175, 2022). "More recently, the implications of MMP-9 upregulation in COVID-19 have been solidified." (PMID 35563537, 2022). "Testing the capability of this ratio to predict the COVID-19 stage by ROC curves, we found the MMP-9/BDNF could be a suitable marker for differentiating stages I/II (AUC 0.7597), stage I/III (AUC 0.9011), and stage I/IV (AUC 0.7727)." (PMID 36438922, 2022). "Moreover, matrix metalloproteinase (MMP-9), which is released by neutrophils during acute lung damage and is elevated in COVID-19 patients’ blood, can cleave CD73 from the cellular membrane generating a soluble protein." (PMID 36248842, 2022). "Studies on MMP-9 may shed some light into the specific roles played by MMPs in severe COVID-19 pathogenesis." (PMID 33800947, 2021). "Moreover, the explorative part of this study presents data of descriptive nature and we lack data on the cellular sources of MMP-9 in these COVID-19 patients." (PMID 34853380, 2021). "In contrast, G-MDSC from severe COVID-19 patients had increased expression of genes associated with granulocyte functions/degranulation and chronic inflammation including Arg1, MMP8, MMP9, S100A8 and A9, MPO, IL18RA, elastase, PRTN3 (azurophilic granule protein 7)." (PMID 34341659, 2021). "Furthermore, it was identified that the MMP-9/BDNF ratio could be used as a potential predictor of severe COVID-19 outcomes, demonstrating its utility in differentiating between disease stages." (PMID 40943488, 2025).
COVID-19 (continued). "Additionally, there is evidence that increased circulating MMP-9 levels may persist even after clinical recovery from COVID-19, indicating their potential role in long-term complications associated with the disease." (PMID 40943488, 2025). "We also predicted that the ratios of MMP-2/BDNF and MMP-9/BDNF could be considered early predictors of COVID-19 mortality, supposing the involvement of metalloproteinase and BDNF in the severe respiratory impairment associated with elevated mortality for COVID-19 infection." (PMID 39596862, 2024). "Besides MMP-9, which has been shown to be associated with a high risk of mortality, others, such as MMP-1, MMP-2, MMP-8, and MMP-13 have also been correlated with disease severity and increased risk of death, especially during the acute phase of COVID-19." (PMID 37372128, 2023). "Furthermore, serum levels of MMP-9 are also related to the severity of COVID-19." (PMID 37372128, 2023). "Furthermore, plasma levels of MMP-9 were increased in those infected with COVID-19." (PMID 37372128, 2023). "However, the cellular origin and molecular pathways involved in MMP-9 release during COVID-19 remain unknown." (PMID 37372128, 2023). "Interestingly, in a study to associate MMP-9 activity with gastrointestinal changes resulting from COVID-19, the results suggested that MMP-9 is not involved in the pathogenic process related to the virus." (PMID 37372128, 2023). "Hence, our findings offer new insights into the molecular mechanisms underlying COVID-19 and sepsis-induced ARDS and suggest CD3, CD247, CD2, CD40LG MMP-9, LCN2, and RETN as the potential targets for neutrophils in developing novel therapies and diagnostic tools for these diseases." (PMID 37822934, 2023). "Interestingly, in a recent network-based systems biology study that set out to identify the molecular targets of drugs that have been proposed as potential candidates for the treatment of COVID-19, MMP-9 emerged as an interacting partner of both chloroquine and melatonin." (PMID 34149717, 2021). "Employing various algorithms, we identified MMP9, CAMP, and CASP1 as NETRGs, demonstrating good discriminatory capacity in COVID-19 and GBS." (PMID 40433617, 2025). "Compared with the healthy group, COVID-19 patient group displayed the significantly lower expression level of BCL2, but significantly higher expression levels of MMP9, ICAM1, and TLR4." (PMID 41411324, 2025). "Consistent with the bioinformatic analysis, CCNB1, CDK1, IRF4, MMP9 and OSM were significantly overexpressed, while LTA was de-expressed in COVID-19 patients compared with healthy controls." (PMID 40300201, 2025). "The expressions of CCNB1, CDK1, IRF4, MMP9 and OSM were significantly higher in COVID-19 samples compared with matched controls, while LTA was down-regulated in GSE171110 training dataset." (PMID 40300201, 2025). "The six biomarkers (CCNB1, CDK1, IRF4, LTA, MMP9 and OSM) can be served as the biomarkers for the treatment and prevention of COVID-19." (PMID 40300201, 2025). "In conclusion, MMP9, CASP1, and CAMP were identified as promising biomarkers and potential targets for therapy of post-COVID-19 GBS." (PMID 40433617, 2025). "In our study, 6 key target genes involved in sepsis and COVID-19 treatment with JHD were identified including AKT1, MMP9, ICAM1, TLR4, BCL2 and HIF1A based on PPI network." (PMID 41411324, 2025). "The findings of our study not only enhance our understanding of the molecular mechanisms of MMP/FasL COVID-19, but also pave the way for potential therapeutic interventions targeting the MMP7/MMP9 and FasL pathways." (PMID 38803919, 2024). "In COVID-19, increased MMP7 and MMP9 activity is thought to contribute to lung damage and inflammation through degrading components of the extracellular matrix in the lungs, leading to tissue injury and impaired lung function." (PMID 38803919, 2024).